HRAS (HRas proto-oncogene, GTPase)
Diseases named in the same sentence as HRAS in open-access papers (continued):
Sharing a sentence is not in itself a finding about the gene and the disease.
tumor (continued). "Patient 1 received the combination of dabrafenib (RAFi) and trametinib (MEKi), and Patient 2 received trametinib (MEKi), treatment recommendations that were guided by tumor genetic profiling (BRAF p.V600E and HRAS p.G13R, respectively)." (PMID 40634537, 2025). "The RAS family of small GTPases (including HRAS, KRAS, and NRAS) plays pivotal roles in tumor progression." (PMID 40919428, 2025). "A heatmap between normal and tumor tissues showed the expression of G6PD, HRAS, NRAS, TIMM9, and MYCN." (PMID 37143953, 2023). "Here, we use bioinformatics to identify a splicing event in another proto-oncogene, HRAS, that is regulated by MYC across multiple tumor types." (PMID 37399401, 2023). "The splicing of HRAS exon 5 was found to be particularly responsive to MYC activity, and the correlation between HRAS splicing and MYC activation is found in other tumor types." (PMID 37399401, 2023). "For example, the well-known downregulated let-7 family plays tumor-suppressive roles in OC by targeting oncogenes, such as c-MYC, HRAS, and KRAS, and cell cycle regulators." (PMID 35549643, 2022). "The findings underscore the differences in the prevalence rates of HRAS, KRAS, and NRAS according to tumor anatomical site and geographical region." (PMID 35600380, 2022). "Both HRAS and HER2 oncogenes enhance the tumor-induced EC chirality weakening compared with the MCF10A wild type." (PMID 36505506, 2022). "Therefore, nsSNPs in HRAS may inhibit the MAPK/ERK pathway causing the restoration of tumor cells to a non-transformed state and increasing the activation of the ERK/MAPK signaling pathway leading to the occurrence and development of tumors." (PMID 36358305, 2022). "To assess the co-dependency of tumour cell lines on SHOC2 and RAS, we correlated chronos scores for SHOC2 and either MRAS or HRAS, KRAS or NRAS from all 1,061 tumour cell lines in DepMap." (PMID 35768504, 2022). "In 35 tumor samples extraction of mRNA was successful and all samples were included in the analysis of relative KRAS and HRAS mRNA expression levels using qRT-PCR." (PMID 33549031, 2021). "In addition to KRAS, both HRAS and NRAS have all been reported to dimerize, but the biologic effects of RAS dimerization and whether a similar mechanism underlies the tumor suppressive functions of WT HRAS and NRAS are untested." (PMID 33924994, 2021). "HRAS, RAF, RAC1, and ERK1/2, as targets of tumor-targeting agents, are closely related to the prevention and treatment of tumors." (PMID 32419796, 2020). "Accordingly, our analysis of a subset of genes that had a significant Z score for similarity to proliferation of tumor cells predicted cell cycle progression through genes such as CDK4, HRAS, IL-4, CSF2, IFNG, IL-6 and STAT3." (PMID 33180876, 2020). "This is in stark contrast to the reported frequencies in the COSMIC database, where KRAS G12D and G12V, HRAS G12D, and BRAF V600E are reported to occur in 8/2585 (0.31%), 4/2585 (0.16%), 0/2159 (0%), and 0/1844 (0%) of IDC tumor samples." (PMID 30813596, 2019). "Both HRAS and SRC are known for their oncogenic activity, thus the inhibitory activity of HRAS toward SRC suggests tumor suppressive activity." (PMID 28815022, 2017). "As we already suggested earlier, a subset of patients (showing gene mutations in PIK3CA, HRAS, KRAS, NRAS and BRAF or ALK translocation) could benefit from a systemic treatment with a PI3K, MEK, BRAF or ALK inhibitor in the case of unresectable or metastasized tumor stage." (PMID 29312620, 2017). "Supporting potential tumor suppressive function for the UPR, HRAS-dependent transformation of primary human melanocytes was potentiated by genetic inhibition of PERK, Ire1 and ATF4." (PMID 27977682, 2016). "The dependency of KRAS mutant tumor cell lines upon CDK6 was readily apparent (rho = −0.38), but was stronger when KRAS, HRAS, NRAS, or BRAF mutant tumor cell line models were combined as a group (rho = −0.43)." (PMID 26947069, 2016).
tumor (continued). "The identification, careful characterisation, and follow-up of cohorts of patients with HRAS/BRAF mutation positive tumours could enable the natural history of such tumours (e.g., absence of malignant or recurrent disease) and so facilitate personalised management of patients with these tumours." (PMID 25883647, 2015). "In patient EP3, HRAS p.Ala121Thr was exclusively detected in the complex tubular region, but not in the serrated fraction, nor on the invasion front, nor in the whole tumour." (PMID 40302146, 2025). "Finaly, the tumor mutational burden (TMB) was low, and no abnormalities were detected in BRAF, NRAS, HRAS, NTRK1/2/3, RET, or TERT." (PMID 40277780, 2025). "HRAS p.Q61L was not present in tumor DNA at diagnosis or at first relapse but was detected with an allele frequency of 27% in the second relapse occurring during lorlatinib treatment." (PMID 39177282, 2024). "Ras protein (HRAS and NRAS) are common oncogenes and mutant RAS could be considered as a driver of tumor initiation and maintenance." (PMID 37143953, 2023). "mRNA levels of RASs (KRAS, HRAS, and NRAS) in LUAD patients with different tumor stages." (PMID 38206735, 2023). "An increase in HRAS mutations was also reported (6.9% for UTUC; 2.8%, for BUC), with most of the HRAS-altered tumours arising from UTUC of the renal pelvis rather than from other anatomic sites." (PMID 38067262, 2023). "The induction of the autophagy process maintains tumor cell development and, consequently, the suppression of KRAS and HRAS could slow down the tumor progression and proliferation partially via autophagy inhibition." (PMID 36497321, 2022). "The loss of Notch1 combined with oncogenic Hras expression induced formation of aggressive tumors, whereas oncogenic HRAS expression alone resulted in small tumors or no tumors at all in a xenograft tumor model." (PMID 34572732, 2021). "Interestingly, the expression of oncogenic HRAS or KRAS has been shown to induce tumor formation in vivo in a doxycycline-dependent manner, and withdrawal of the drug resulted in tumor shrinkage." (PMID 33793658, 2021). "Furthermore, our in vitro data supported the finding that SIRT1 overexpression markedly hampered HRAS-induced tumorigenic activities, indicating SIRT1 as a tumor suppressor in the oncogenic RAS activation setting as well." (PMID 32276460, 2020). "We also observed mutations in HRAS at codons 61 and 12 (two and one samples, respectively), and a single BRAF V600E mutation in an ER− tumour, although the two genes did not meet Mut-driver criteria." (PMID 27161491, 2016). "Takentogether, these results suggested that DOT1L is able to induce malignanttransformation of breast epithelial cells, regardless of cooperation with HRAS,as a regulator of tumour-initiating ability of breast CSC." (PMID 26199140, 2015). "We screened the bulk of tumour present in three additional ISS cases for activating mutations in FGFR3 and HRAS, but no sequence variations were identified in these samples." (PMID 21706474, 2011).
tumor (continued). "Importantly, this unbiased screening identified several hits that positively regulate PRMT5 expression, including oncoproteins such as HRAS and BRAF, whereas tumor suppressors like KEAP1 were identified as top-scoring hits that negatively regulate PMRT5 levels." (PMID 40091834, 2025). "Retrospective sequencing of lobectomy and postmortem tumor samples (posterior mediastinum and retroperitoneum) (“Primary subclone” and “Autopsy”, respectively) showed HRAS p.G13R in both specimens, without any copy number changes at the HRAS locus." (PMID 40634537, 2025). "Molecular VAF assays were developed for the quantitative detection of RAS variants at single-nucleotide resolution positive for NRAS, HRAS, and KRAS in tumor tissues but not in the adjacent healthy tissue, which were verified by Sanger sequencing (eFigure 1 in Supplement 1)." (PMID 38758552, 2024). "The expression levels of EGF-EGFR-RAS signaling marker genes EGF, EGFR, HRAS, RASSF1 and STK4 in the HLX22 and HLX02 combination-treated cells decreased, suggesting that HLX22 in combination with HLX02 inhibited EGF-EGFR-RAS signaling to suppress tumor proliferation, survival, and invasion." (PMID 38982548, 2024). "Therefore, the aim of this study was to determine the sensitivity and specificity of IHC using SP174 to detect RAS Q61R in CAA tumor tissue and a lack of immunoreactivity with OSCC, including tumors that harbor a closely related HRAS p.Q61L mutation." (PMID 37901104, 2023). "Putative oncogenic and targetable mutations could be found in individual tumor samples in FGFR2 (SNUC, SNSCC non-keratinizing), FGFR3 (SNSCC-associated with ISP), MAP1K2 (SNAC), MET (ISP-associated SNSCC), MAP2K1 (SNAC) and HRAS (SNSCC keratinizing and ITAC)." (PMID 34885191, 2021). "Certain miRNA also functions as tumor suppressors, for instance, the let 7 family suppresses tumor development and metastasis via targeting key oncogenic genes like high-mobility group AT-hook 2 (HMGA2), members of the RAS family (NRAS, KRAS, and HRAS), and MYC." (PMID 35145899, 2021). "In addition to the enrichment analysis, using a maximum-likelihood dN/dS method we detected signals of positive selection for mutations within CASP8 and HRAS in samples with TMD, but not in expanding tumor samples." (PMID 34307377, 2021). "The decrease in tumor expression of p-class I PI3K/p-mTOR/p-p70S6K and increase of p-ERK validated the results using bioinformatics analysis and confirmed the observation in vitro, further highlighting the role of mutant HRAS in cisplatin sensitivity of T24 xenografts in response to pterostilbene." (PMID 33036162, 2020). "To test our hypothesis that therapeutic targeting of oncogenic HRAS could be a clinically relevant choice for the patient, we used subcutaneous BC159-T#3 PDX, which recapitulated the patient tumor with respect to tumor cell morphology, the expression of HRASQ61R protein, and basal squamous subtype." (PMID 32460812, 2020). "We identified seven oncogenes (NRAS, EGFR, RXRA, HRAS, KRAS, AKT1, ERBB2; q<0.10) and seven putative tumor suppressor genes (ARID1A, TXNIP, CTNNB1, PIK3RI, CDKN2A, KLF5, STAG2; q<0.10) significantly regulated between tumor and control, which were formerly reported to be altered in BC." (PMID 30419021, 2018).
tumor (continued). "Furthermore, as HRAS is a common mutation site in RC, the observed negative correlation between HRAS and GLTP may be associated with the tumor suppressor mechanism of GLTP." (PMID 40963625, 2025). "Therefore, a plausible hypothesis is that mutations in these genes—in particular HRAS, EGFR, and RB1—were coincidental findings in individual tumours, and are not recurrent driver events in EP tumourigenesis." (PMID 34045664, 2022). "For instance, tipifarnib and other FTIs have been suggested to act as antiangiogenic agents in several tumor types including HNSCC, but the mechanisms are yet to be elucidated and may be hard to delineate from indirect downstream consequences of inhibiting another target, such as HRAS." (PMID 34771475, 2021). "Thus, PIK3CA, NRAS, HRAS, PTEN, MET, and IDH2 R140Q mutations might be related to the metastasis process rather than primary tumor development." (PMID 29290998, 2017). "Nevertheless, we could conclude that at least in vitro TCF7L1 is able to override HRAS-induced senescence mainly through its DNA- and Groucho/TLE corepressor binding domains and not on its β-catenin binding domain, similarly to its ability to promote tumor growth." (PMID 28467300, 2017). "Their effect on anchorage-independent growth, which is of significant importance in tumour biology, was summarised as follows: KRAS4A >/= NRAS >>> KRAS4B = HRAS = no growth." (PMID 32772213, 2020). "Notably, upregulated genes in relapsed SW837 xenograft tumor included MRAS, a homologue of the RAS family of GTPases37, and RasGRP1, a Ras GEF38,39, but not NRAS or HRAS." (PMID 39103541, 2024). "However, tumours within Cluster 2 (NF1, RET or HRAS) had no differentially methylated probes in any comparisons between this group." (PMID 38124114, 2023).
adenocarcinoma (17 papers, 1989 to 2023). A common cancer characterized by the presence of malignant glandular cells. "Their results revealed differences in mutation frequency between adenocarcinoma and SCC, and as was expected, the characteristic activating mutations of adenocarcinoma such as KRAS, HRAS, NRAS, and EGFR were identified only in 3% of SCCs." (PMID 32604993, 2020).
infection (14 papers, 2009 to 2023). The state of being infected such as from the introduction of a foreign agent such as serum, vaccine, antigenic substance or organism. "HRAS (G12V) was well expressed, and infection of NIH-3T3 cells with two kinds of retroviruses including sh-RNA against murine Nkiras2 caused effective reductions in Nkiras2 protein expression." (PMID 34667224, 2021). "To validate the hit, we first repeated the infection of AALE cells with the individual ATM shRNA in the absence of HRAS." (PMID 27922010, 2016).
neurodegenerative disease (4 papers, 2018 to 2024). A disorder of the central nervous system characterized by gradual and progressive loss of neural tissue and neurologic function. "Rho GTPases, including HRAS, have significant therapeutic potential in the treatment of neurodegenerative diseases, as they have been implicated in nearly all stages of brain development." (PMID 37214397, 2023).
cardiovascular disease (2 papers, 2022 to 2025). "NOS3, etc., controlled cardiovascular disease pathways, and HRAS, etc., played a key role in hormone signalling networks." (PMID 41155650, 2025).
gastrointestinal tumors (2 papers, 2018 to 2023). "HRAS overexpression predicts the response of gastrointestinal tumors to lenvatinib treatment." (PMID 37341987, 2023).
benign neoplasms of (1 paper, 2022). "Notably, KRAS mutations, HRAS mutations, and HPV infection were mutually exclusive in benign neoplasms of the head and neck." (PMID 35600380, 2022).
hematological tumors (1 paper, 2021). "Similar oncogenic alterations in KRAS, NRAS and HRAS genes are strong causative drivers in a broad variety of solid and hematological tumors with mostly aggressive behavior." (PMID 34771672, 2021).
renal diseases (1 paper, 2025). "Also, renal diseases were only observed in patients with KRAS mutations, while the development of skeletal abnormalities was significantly associated with mutations in the HRAS gene." (PMID 41438146, 2025).
HRAS also shares sentences with these, for which no sentence is quoted: cardiofaciocutaneous syndrome (8 papers); skin cancer (8); paraganglioma (7); atherosclerosis (5); achondroplasia (4); diabetic retinopathy (4); invasive ductal carcinomas (4); transitional cell carcinoma (4); viral infection (4); adenoid cystic carcinoma (3); arterial hypertension (3); chronic myelogenous leukemia (3); genetic disorder (3); keratoacanthoma (3); multiple myeloma (3); neurodevelopmental disorder (3); pituitary cancer (3); Pleural effusion (3); rectal cancer (3); sebaceous nevus (3); acanthosis nigricans (2); acute lymphoblastic leukemia (2); autoimmune disease (2); carcinoma in situ (2); cardiac hypertrophy (2); cardiomyopathy (2); cognitive deficits (2); colorectal adenocarcinoma (2); cyst (2); dermatitis (2).
A further 183 diseases each share a sentence with HRAS in 2 papers or fewer.